WDR48 (WD repeat domain 48)
Description:
Regulator of deubiquitinating complexes, which acts as a strong activator of USP1, USP12 and USP46. Enhances the USP1-mediated deubiquitination of FANCD2; USP1 being almost inactive by itself. Activates deubiquitination by increasing the catalytic turnover without increasing the affinity of deubiquitinating enzymes for the substrate. Also activates deubiquitinating activity of complexes containing USP12. In complex with USP12, acts as a potential tumor suppressor by positively regulating PHLPP1 stability. Docks at the distal end of the USP12 fingers domain and induces a cascade of structural changes leading to the activation of the enzyme. Together with RAD51AP1, promotes DNA repair by stimulating RAD51-mediated homologous recombination. Binds single-stranded DNA (ssDNA) and double-stranded DNA (dsDNA). DNA-binding is required both for USP1-mediated deubiquitination of FANCD2 and stimulation of RAD51-mediated homologous recombination: both WDR48/UAF1 and RAD51AP1 have coordinated role in DNA-binding during these processes. Together with ATAD5 and by regulating USP1 activity, has a role in PCNA-mediated translesion synthesis (TLS) by deubiquitinating monoubiquitinated PCNA. Together with ATAD5, has a role in recruiting RAD51 to stalled forks during replication stress. (Microbial infection) In case of infection by Herpesvirus saimiri, may play a role in vesicular transport or membrane fusion events necessary for transport to lysosomes. Induces lysosomal vesicle formation via interaction with Herpesvirus saimiri tyrosine kinase-interacting protein (TIP). Subsequently, TIP recruits tyrosine-protein kinase LCK, resulting in down-regulation of T-cell antigen receptor TCR. May play a role in generation of enlarged endosomal vesicles via interaction with TIP. In case of infection by papillomavirus HPV11, promotes the maintenance of the viral genome via its interaction with HPV11 helicase E1.
Synonyms: KIAA1449; UAF1; P80; SPG60; Bun62
Tractability: Small molecule: a structure with a bound ligand is known; a high-quality ligand is known. PROTAC: ubiquitination databases record sites on it; its protein half-life has been measured; a small molecule that binds it is known.
Target class: Reader; Epigenetic regulator; Methyl-lysine/arginine binding protein; WDR domain
Chemical probes: ML323 (high quality)
Gene: Protein-coding gene on chromosome 3 (39,051,999 to 39,096,671, forward strand). Ensembl gene ENSG00000114742.
Subcellular location: Nucleus; Cytoplasm; Lysosome; Late endosome
Subcellular location (Human Protein Atlas): Vesicles
Pathways (Reactome):
DNA Repair: Fanconi Anemia Pathway; Recognition of DNA damage by PCNA-containing replication complex
Disease: Signaling by cytosolic PDGFRA and PDGFRB fusion proteins
Metabolism of proteins: Ub-specific processing proteases
Gene Ontology:
Molecular function: deubiquitinase activator activity; DNA binding; double-stranded DNA binding; protein binding; single-stranded DNA binding; ubiquitin binding
Biological process: DNA damage response; positive regulation of canonical Wnt signaling pathway; positive regulation of double-strand break repair via homologous recombination; positive regulation of receptor signaling pathway via JAK-STAT; double-strand break repair via homologous recombination
Cellular component: cytoplasm; late endosome; lysosome; nucleus; peptidase complex; cytosol; nucleoplasm; plasma membrane
Genetic constraint (gnomAD): Loss-of-function variants: 17 observed, 76.08 expected, observed/expected ratio (o/e) 0.22, 90% interval 0.15 to 0.34. The upper end of that interval is the gene's LOEUF score, 0.34, which puts it in group 1 of 6, group 1 being the genes least tolerant of losing a copy. Missense variants: 464 observed, 743.19 expected, observed/expected ratio (o/e) 0.62, 90% interval 0.58 to 0.67. Synonymous variants: 255 observed, 263.03 expected, observed/expected ratio (o/e) 0.97, 90% interval 0.87 to 1.08.
Homologues: Orthologues: dog WDR48 (100% identical), rabbit WDR48 (99% identical), mouse Wdr48 (99% identical), guinea pig WDR48 (98% identical), chimpanzee WDR48 (98% identical), pig WDR48 (98% identical), rat Wdr48 (97% identical), macaque WDR48 (97% identical), zebrafish wdr48b (93% identical), tropical clawed frog wdr48 (92% identical), zebrafish wdr48a (71% identical), zebrafish WDR48 (66% identical), and 2 more.
Diseases named in the same sentence as WDR48 in open-access papers:
WDR48 is named in the same sentence as 25 diseases in open-access papers, as found by Europe PMC text mining. Sharing a sentence is not in itself a finding about the gene and the disease. The quoted sentences say what the papers report.
Fanconi anemia (11 papers, 2012 to 2026). Fanconi anemia (FA) is a hereditary DNA repair disorder characterized by progressive pancytopenia with bone marrow failure, variable congenital malformations and predisposition to develop hematological or solid tumors. "Because of this crucial role of the WDR48 gene, and the association that we found of a low expression of WDR48 with poor prognosis, a defective Fanconi Anemia repair pathway may play a role in the malignant transformation of UM." (PMID 31382494, 2019). "USP1 and its cofactor USP1‐associated factor 1, also called WD repeat domain 48 (WDR48), function as regulators in the processes of the DNA damage response, especially in the translation synthesis process and the Fanconi anaemia pathway." (PMID 32951278, 2020). "Although originally described as an endosomal protein, WDR48 has subsequently been isolated from other cellular compartments, including as a chaperone for USP1 in the nucleus as a component of the Fanconi anemia DNA repair pathway." (PMID 25855980, 2015). "Interestingly, UAF1/WDR48 can fully activate the DUB activity of USP1, which regulates the Fanconi anemia DNA repair pathway, but only weakly stimulates the catalytic activity of USP46 and USP12, whereas full activation of USP12 requires ternary complex formation with both UAF-1/WDR48 and WDR20." (PMID 23316392, 2012).
breast carcinoma (2 papers, 2022 to 2024). "To validate the results of our screens, we used Crispr/Cas9 technology to knockout (KO) the USP12, USP46, WDR20, and WDR48 genes either individually or in combination in at least two different mouse fibroblast and human breast cancer MDA-MB-231 cell clones, respectively." (PMID 39506038, 2024).
colorectal cancer (2 papers, 2013 to 2022). A primary or metastatic malignant neoplasm that affects the colon or rectum. "Importantly, we found a WDR48 somatic mutation (L580F) that is defective in stabilizing PHLPP1 in colorectal cancers, supporting a WDR48 role in tumor suppression." (PMID 24145035, 2013).
HCMV infection (2 papers, 2020 to 2023). "Among these proteins, STEAP3, BORCS7, FAM172A, RELL1, and WDR48 were further demonstrated to affect HCMV infection." (PMID 32481657, 2020). "During the late phase of HCMV infection, STEAP3, BORCS7, FAM172A, RELL1 and WDR48 were differentially expressed between Han- and HanUL138del-infected cells, and further functional studies indicated that all of these proteins could affect HCMV infection." (PMID 32481657, 2020).
colon adenocarcinoma (1 paper, 2013). "Among these mutations, we identified that an L580F mutation of WDR48 found in colon adenocarcinoma is defective in stabilizing PHLPP1." (PMID 24145035, 2013). "In fact, we identified a disease-associated WDR48 mutation in colon adenocarcinoma that is defective in binding and maintaining optimal PHLPP1 levels in cells." (PMID 24145035, 2013).
dysferlinopathy (1 paper, 2023). "Analysis of muscle transcripts from patients with dysferlinopathy identified 6 downregulated DEGs (RFC4, RFC5, ATAD5, TP53BP1, WDR48, and RAD17) related to the cellular response to DNA damage stimulus." (PMID 38125829, 2023).
hepatoma (1 paper, 2022). "However, the role of WD repeat domain 48 (WDR48) in hepatocellular carcinoma (HCC) and its molecular basis remain to be further investigated." (PMID 36403194, 2022). "Therefore, the deubiquitination effect of WDR48 on c‐Myc is very important for WDR48‐mediated hepatoma proliferation and EMT." (PMID 36403194, 2022). "After the use of si‐c‐Myc in hepatoma cells, the proliferation and EMT signal of hepatoma cells mediated by the overexpression of WDR48 decreased." (PMID 36403194, 2022).
tumor (14 papers, 2013 to 2025). "USP1 is associated with UAF1 (WDR48, also named USP1 associated factor 1) in tumor cells, and this interaction is important for its cellular function." (PMID 35307036, 2022). "Of potential functional relevance, in lymphocytes and blood, the rs1274963A risk allele was associated with reduced WDR48 expression, a gene shown to induce apoptosis and suppress tumour cell proliferation." (PMID 26956414, 2016). "With regard to associations between gene expression and tumor diameter, we noticed an association between low expression of WDR48 and XPC and a large LBD (p = 0.01 and p = 0.004, respectively), while a high expression of CENPX correlated with a large LBD (p = 0.02)." (PMID 31382494, 2019). "Together, these results suggest that WDR48 acts as a potential tumor suppressor by stabilizing PHLPP1, and mutations that disrupt its interaction with substrates may contribute to tumorigenesis." (PMID 24145035, 2013). "The average optical density of WDR48 protein in tumour tissues was stronger than that in adjacent tissues." (PMID 36403194, 2022). "The key role of WDR48 in tumour progression urged us to determine the mechanism by which WDR48 promoted cell growth and metastasis." (PMID 36403194, 2022). "The results showed a significant decrease in tumour growth and weight in the group injected with si‐WDR48." (PMID 36403194, 2022). "When the subcutaneous tumour of nude mice grew to about 3 mm in diameter 5 days after inoculation, si‐NC or si‐WDR48 was injected into the developing tumour." (PMID 36403194, 2022). "We found that WDR48 expression was upregulated in 75% tumour tissues compared with their adjacent non‐tumour tissues." (PMID 36403194, 2022). "USP1 and its cofactor WDR48 are involved in the tumour progression of HCC by deubiquitinating and stabilizing their substrates." (PMID 32951278, 2020). "Although proteins such as FANCD2, PCNA, notch receptor, and histones H2A and H2B were reported to be deubiquitinated by the WDR48·DUB complex, the cellular functions of WDR48 and its role in tumor suppression were not completely known." (PMID 24145035, 2013). "Conversely, if PTEN (as a tumor suppressor) is deleted, the cell might improve in tumorigenesis; with the inhibition of WDR48 the cell might survive, but it is likely to have functional impairment." (PMID 33992077, 2021). "To further establish the role of WDR48 as a tumor suppressor and its dependence on PHLPP1 regulation, we screened for WDR48 mutations in human cancers that might be defective in regulating this pathway." (PMID 24145035, 2013). "WDR48 regulates deubiquitinating complexes and may have a role in tumor suppression." (PMID 26186006, 2015). "Thus, WDR48 might function as tumor suppressor by positively regulating the stability of several tumor suppressor proteins in the cell." (PMID 24145035, 2013). "Low expression of WDR48 and XPC was related to a large tumor diameter (p = 0.01 and p = 0.004, respectively), and a mixed/epithelioid cell type (p = 0.007 and p = 0.03, respectively)." (PMID 31382494, 2019). "Together, our results reveal WDR48 and USP12 as novel PHLPP1 regulators and potential suppressors of tumor cell survival." (PMID 24145035, 2013). "We demonstrated that the WDR48·USP12 complex deubiquitinates and regulates PHLPP1 levels, which is essential for their possible tumor suppressor function." (PMID 24145035, 2013). "Significance: WDR48 was identified as novel PHLPP1 regulator, which is critical in understanding its role as tumor suppressor in human cancers." (PMID 24145035, 2013). "In our study, in addition to identifying WDR48 as a physical partner of PHLPP1 in cells, functionally we also demonstrated its ability to act as a potential tumor suppressor." (PMID 24145035, 2013). "Functionally, we show that WDR48 and USP12 suppress proliferation of tumor cells." (PMID 24145035, 2013). "We revealed WDR48 as an additional regulator of PHLPP1 and a potential tumor suppressor." (PMID 24145035, 2013).
tumor (continued). "Further, the L580F mutant significantly failed to suppress the rate of tumor cell proliferation compared with wild type WDR48." (PMID 24145035, 2013). "Thus, WDR48·USP12, being a deubiquitinase complex and a positive regulator of PHLPP1 stability, might function as a tumor suppressor complex as well." (PMID 24145035, 2013).
cancer (9 papers, 2012 to 2025). A tumor composed of atypical neoplastic, often pleomorphic cells that invade other tissues. "Ubiquitin specific peptidase 1 (USP1), a member of the DUBs, usually forms with a complex with USP1-associated factor 1 (UAF1, also known as WDR48) and plays a key role in promoting the development of some cancers." (PMID 34154657, 2021). "In the future it would be very interesting to screen different human cancers for additional WDR48 mutations that might not only be defective in maintaining PHLPP1 function but also other substrates such as BRCA1, FANCD2, H2A/H2B, PCNA, and notch receptor." (PMID 24145035, 2013). "This may suggest that the use of a PTEN inhibitor in a WDR48-deficient cancer could result in an effective treatment, but not the other way round (i.e., using a WDR48 inhibitor in a PTEN-deficient cancer)." (PMID 33992077, 2021).
WDR48 also shares sentences with these, for which no sentence is quoted: viral infection (3 papers); cervical cancer (1); colitis (1); Flavivirus Infections (1); gastric cancer (1); glioblastoma (1); infection (1); lung carcinoma (1); non-small cell lung carcinoma (1); osteosarcoma (1); ovarian carcinoma (1); prostate carcinoma (1); schizophrenia (1); ulcer (1); uveal melanoma (1); viral diseases (1).